AMELY (amelogenin Y-linked)
Description:
Plays a role in biomineralization. Seems to regulate the formation of crystallites during the secretory stage of tooth enamel development. Thought to play a major role in the structural organization and mineralization of developing enamel.
Synonyms: AMGL; AMGY
Tractability: Antibody: UniProt places it where antibodies can reach, with medium confidence; UniProt predicts a signal peptide or a membrane-spanning region; its Gene Ontology location is reachable by antibodies, with medium confidence.
Gene: Protein-coding gene on chromosome Y (6,865,918 to 6,911,752, reverse strand). Ensembl gene ENSG00000099721.
Subcellular location: Secreted, extracellular space, extracellular matrix
Gene Ontology:
Molecular function: structural constituent of tooth enamel
Biological process: enamel mineralization
Cellular component: extracellular matrix; non-collagenous component of interstitial matrix
Homologues: Orthologues: chimpanzee AMELY (98% identical), macaque AMELY (91% identical), pig AMELX (83% identical), guinea pig Amelx (48% identical). Paralogues in human: AMELX (88% identical).
Diseases named in the same sentence as AMELY in open-access papers:
AMELY is named in the same sentence as 8 diseases in open-access papers, as found by Europe PMC text mining. Sharing a sentence is not in itself a finding about the gene and the disease. The quoted sentences say what the papers report.
hepatocellular carcinoma (1 paper, 2013). A malignant tumor that arises from hepatocytes. "Amelogenin Y-linked (AMELY) has been identified to be one of the significantly highly expressed (fold change ≥2) genes in human hepatocellular carcinoma (HCC)." (PMID 23426651, 2013).
hypogonadism (1 paper, 2020). A disorder characterized by decreased function of the gonads. "Structural rearrangements involving AMELY, mapping on the chromosome Yp11.2, have been found in patients with hypogonadism, although a direct link between the phenotype and the rearrangement has not been proven." (PMID 33574797, 2020).
tumor (3 papers, 2013 to 2025). "Nonsynonymous mutations were found in the genes AMELY, DDX3Y, RPS4Y2, TBL1Y in African tumors (5 samples: 4 HRPCa 1 LRPCa), and in UTY in one European HRPCa tumor." (PMID 40454088, 2025). "Here, we found nonsynonymous variants impacting AMELY, DDX3Y, RPS4Y2, and TBL1Y in five African tumors (4.7%), and UTY in a single European tumor (1.8%), highlighting the potential for these chrY genes as ancestry-specific cancer driver candidates." (PMID 40454088, 2025). "Biological processes and occurrence numbers of GO in non-tumor tissues with activated low expression of AMELY upstream regulation networks and the corresponding HCC tissues with high expression (fold change ≥2) were identified and computed." (PMID 23426651, 2013). "Among odontogenesis related genes, AMBN is specifically expressed in T3, other genes including ENAM, AMELX and AMELY are not expressed in all the tumor cells." (PMID 39223689, 2024).
AMELY also shares sentences with these, for which no sentence is quoted: cancer (2 papers); infertile (2); male infertility (2); amelogenesis imperfecta (1); spermatogenic failure (1).